SHBG (sex hormone binding globulin)
Diseases named in the same sentence as SHBG in open-access papers (continued):
Sharing a sentence is not in itself a finding about the gene and the disease.
endometriosis (continued). "In order to identify non-additive genetic effects that determine the risk of endometriosis, antagonistic/synergistic SNP-SNP interactions (SNP-SNPinter) of the studied SHBG-significant SNPs were analyzed." (PMID 41373783, 2025). "Such SHBG-mediated effects will directly determine the severity of the biological influences of androgens/estrogens in the organism, including those significant for endometriosis biology." (PMID 41373783, 2025). "This may be one of the pathophysiological mechanisms of the rs440837 (A > G) ZBTB10 (with rs7013042) communicating with the SHBG level and their involvement in endometriosis pathogenesis due to this." (PMID 41373783, 2025). "Importantly, endometriosis-causal SNP rs440837 (A > G) ZBTB10 itself and the strongly linked variant rs7013042 manifest functional activity in the liver, which is the organ of SHBG formation." (PMID 41373783, 2025). "Given that endometriosis is an estrogen-dependent condition and PA can increase Sex Hormone-Binding Globulin (SHBG), it is postulated that PA may reduce bioavailable estrogens." (PMID 39062050, 2024). "In women with endometriosis, exercise may further prove beneficial as it increases sex hormone-binding globulin levels, thus reducing estrogen levels." (PMID 37391793, 2023). "This suggests a possible pathway through which red meat, which was shown to reduce SHBG concentrations and increase estradiol, may benefit women with endometriosis suffering from pain." (PMID 37834048, 2023). "In addition, we also found enrichment of sex-related signals such as GO_REGULATION_OF_GONAD_DEVELOPMENT (adjusted p = 0.023), endometriosis (adjusted p = 7.3 × 10−4), sex hormone-binding globulin levels (adjusted p = 0.003), and sex hormone levels (adjusted p = 0.024)." (PMID 35903355, 2022). "Furthermore, two causal loci for endometriosis (rs34670419 ZKSCAN5 and rs727428 SHBG) and four polymorphisms that are in close linkage disequilibrium with them may modulate seven gene splicing in a tissue-specific manner." (PMID 36430184, 2022). "Endometriosis patients had lower LH relative to follicle-stimulating hormone (FSH), higher sex hormone-binding globulin (SHBG), higher serum oxytocin, lower serum testosterone, and lower anti-Müllerian hormone (AMH)." (PMID 34367069, 2021). "On the contrary, caffeine consumption has been linked to increased sex hormone-binding globulin (SHBG) concentrations and decreased testosterone levels, raising concerns about its potential negative impact on hormone-dependent conditions like endometriosis." (PMID 40565701, 2025).
COVID-19 (14 papers, 2021 to 2025). A disease caused by infection with severe acute respiratory syndrome coronavirus 2. "In the minimally adjusted model (Model 1) which included exposure variable, age, region, and interaction of region with time, total testosterone, SHBG, and cFT were associated with risk of dying from COVID-19 (Model 1: P values for overall trends <0.05)." (PMID 35536887, 2022). "Middle-aged to older men with the highest premorbid serum total testosterone and SHBG concentrations are at greater risk of COVID-19-related mortality." (PMID 35536887, 2022). "Null association was also noticed between SHBG and COVID-19 susceptibility (OR = 0.91; 95% CI: 0.80–1.04, p=0.182), hospitalization (OR = 0.86; 95% CI: 0.66–1.11, p=0.255), risk of severity (OR = 0.92; 95% CI: 0.65–1.29, p=0.618)." (PMID 36250974, 2022). "The association of SHBG with COVID-19 mortality risk was similar to that of total testosterone, reflecting the close correlation between these two variables." (PMID 35536887, 2022). "U-shaped associations of total testosterone and SHBG concentrations with risk of death from COVID-19 were apparent." (PMID 35536887, 2022). "Our findings that higher SHBG was associated with COVID-19-related mortality are consistent with higher SHBG being a biomarker for several poorer health outcomes in men." (PMID 35536887, 2022). "In conclusion, total and free testosterone levels in men, and SHBG levels in all patients, are associated with outcome of admitted patients with COVID-19." (PMID 34449505, 2021). "Our study shows that lower levels of total and free testosterone were associated with fatal outcome in men who died of COVID-19, as were lower levels of SHBG in both men and women." (PMID 34449505, 2021). "Low SHBG levels were associated with mortality rate in patients with COVID-19, and low total and free testosterone levels were associated with mortality in men." (PMID 34449505, 2021). "In community-dwelling men aged 40–69 years, serum total testosterone and SHBG concentrations measured a decade or more prior to the onset of the SARS-CoV-2 pandemic were associated with risk of dying from COVID-19, independently of sociodemographic, lifestyle, and medical factors." (PMID 35536887, 2022). "Low T/LH, FSH/LH, and SHBG serum levels and high LH, and E2/T levels may increase the risk of COVID-19." (PMID 36303865, 2022). "Serum samples were not available for assays of luteinizing hormone, follicle stimulating hormone, SHBG, and other hormones to investigate the mechanisms by which COVID-19 affects the hypothalamic-pituitary-testicular axis." (PMID 39911523, 2025). "We found higher plasma SHBG levels in COVID-19 male patients at diagnosis, which decreased during follow-up." (PMID 37896963, 2023). "The dihydrotestosterone (DHT) levels were transiently reduced, while the sex hormone-binding globulin levels were decreased in post-COVID-19 male patients." (PMID 37896963, 2023). "Observed SHBG levels were below reference values in both the COVID-19 and post-COVID-19 patients and reflected their reduced testosterone and DHT levels." (PMID 37896963, 2023). "The SHBG levels were increased at diagnosis and decreased in the post-COVID-19 male patients (p < 0.01)." (PMID 37896963, 2023). "Lower levels of SHBG were apparent in the DB arm as compared to the OL 100-mg arm, consistent with the COVID-19-related drug kit delays that occurred in the DB arms." (PMID 37845512, 2023). "Sex hormone-binding globulin (SHBG) was also higher in the control group, which is in contrast with previous reports of increased SHBG serum levels in male COVID-19 patients." (PMID 37628421, 2023). "This study aimed to examine associations of sex hormone, sex hormones-binding globulin (SHBG), insulin-like growth factor-1 (IGF-1), and COVID-19 risk." (PMID 36250974, 2022).
COVID-19 (continued). "Overall, this study demonstrated that changes in sex hormone levels, such as decreased T/LH, FSH/LH, and SHBG levels and elevated LH, and E2/T levels, were strongly correlated with the severity and prognosis of COVID-19." (PMID 36303865, 2022). "We evaluated two studies that reported SHBG values in 79 COVID-19 patients." (PMID 38345682, 2024). "Additionally, the likelihood of elevated LH and E2/T serum levels and decreased T/LH, FSH/LH, and SHBG levels increases with COVID-19 clinical severity." (PMID 38738039, 2024). "A non-linear relationship of SHBG with risk of dying from COVID-19 was present in men in quintile 4 of SHBG having a lower risk compared to men in quintile 5 but no further reduction in risk across quintiles 1–3 of SHBG." (PMID 35536887, 2022). "We analysed the associations of total testosterone, SHBG, and calculated free testosterone (cFT), assessed in UK Biobank men some years prior to the pandemic, with incidence of SARS-CoV-2 infection and death related to COVID-19." (PMID 35536887, 2022). "The aim of our study was to monitor the relevant parameters of female fertility (sex and other steroids, LH, FSH, SHBG, Antimüllerian hormone and antral follicle count) before and then 2–4 months after the third dose of vaccination against COVID-19 in a group of 25 healthy fertile woman." (PMID 36142820, 2022). "Higher SHBG was also associated with COVID-19 mortality risk (P = 0.008), but cFT was not (P = 0.248)." (PMID 35536887, 2022). "In conclusion, total testosterone and SHBG concentrations were non-linearly associated with COVID-19-related mortality risk in middle-aged to older men." (PMID 35536887, 2022). "The ANOVA model showed that women who had experienced a COVID-19 infection had significantly higher plasma levels of DHT and DHEA, and significantly lower levels of 5α-dihydroprogesterone, estrone, estradiol and SHBG at the time of the second sampling (after 3rd dose of COVID-19 vaccine)." (PMID 36142820, 2022). "Low SHBG levels seem to correlate with worse COVID-19 prognosis." (PMID 36303865, 2022). "In 28.2% of male COVID-19 patients, SHBG levels were elevated, which might suggest masked testosterone deficiencies in some patients." (PMID 34402750, 2021). "Reduced adherence after the COVID-19 diagnosis, increased testosterone clearance, and/or changes in sex hormone binding globulin (SHBG) levels induced by the COVID-19 infection could potentially contribute to lower testosterone levels in the TRT group after the COVID-19 diagnosis." (PMID 39911523, 2025). "Men exhibited lower than expected serum TT and SHBG levels in both groups, indicating that COVID-19, systemic inflammation, and certain medications, such as glucocorticoids, may hamper acutely testosterone secretion and transport, leading to male hypogonadism in all." (PMID 38243977, 2024). "The risk of COVID-19 may be increased by low serum levels of low Testosterone/Luteinizing Hormone (LH) (T/LH), follicular stimulating hormone (FSH)/LH, and sex hormone-binding globulin (SHBG), as well as high levels of LH and Estrogen/Testosterone (E2/T)." (PMID 38738039, 2024). "Thus, low plasma SHBG level predicts the severity of COVID-19." (PMID 36303865, 2022). "In contrast to SHBG, DHT was positively correlated with CK (r = 0.365, p = 0.018) in post-COVID-19 patients." (PMID 37896963, 2023). "Testosterone, SHBG, IGF-1, and COVID-19 outcomes in Mendelian randomization (MR) analyses adjusting BMI." (PMID 36250974, 2022). "According to analysis of the included studies, patients with COVID-19 had significantly low T/LH, FSH/LH, and SHBG levels and high levels of LH, and E2/T, but their levels of FT, FSH, PRL, E2, and progesterone were not affected." (PMID 36303865, 2022). "Specifically, COVID-19 patients showed a significant decrease in the levels of T/LH, FSH/LH, and SHBG hormones." (PMID 36303865, 2022). "Sex hormones, SHBG, IGF-1, and COVID-19 outcomes in Mendelian randomization (MR) analyses." (PMID 36250974, 2022).
COVID-19 (continued). "The associations were non-linear; men with the highest total testosterone and SHBG concentrations had moderately higher risks of COVID-19-related mortality." (PMID 35536887, 2022). "Additionally, the greater is the clinical severity of COVID-19, the higher is the probability of increases in LH, and E2/T serum levels and decreases in T/LH, FSH/LH, and SHBG levels." (PMID 36303865, 2022).
male infertility (12 papers, 2016 to 2025). The inability of the male to effect fertilization of an ovum after a specified period of unprotected intercourse. "Genetic mutations in SHBG, particularly at the rs6259 and rs727428 loci, have been linked to male infertility." (PMID 39057081, 2024). "The genetic mutations in SHBG genes, more specifically mutated rs6259 and rs727428 loci, are involved in male infertility." (PMID 38067423, 2023). "The loss of testosterone bioavailability due to SHBG leads to severe consequences, including male infertility, prostate cancer, and gonadal dysfunction." (PMID 38067423, 2023). "Additionally, mutations, including single nucleotide polymorphisms, which alter SHBG expression and functions that regulate sperm count and semen quality, are associated with human male infertility." (PMID 36836833, 2023). "This imbalance, together with elevated SHBG levels, ends up causing male infertility." (PMID 27752262, 2016). "The role of SHBG in diagnosing primary male infertility can be a more precise factor to determine the accuracy of decreased semen parameters." (PMID 40427034, 2025). "While numerous studies have used in silico analyses of distinct disease-causing receptor proteins to predict their bioactive molecules and inhibitors, few have examined the role of potent natural inhibitors of the SHBG protein to prevent male infertility." (PMID 36836833, 2023). "Only a few studies have been done using the SARS-CoV-2 inhibitors to identify the SHBG inhibitor, which is thought to be the main protein responsible for male infertility." (PMID 36836833, 2023). "Male infertility is significantly influenced by the plasma-protein sex hormone-binding globulin (SHBG)." (PMID 36836833, 2023). "A decline in SHBG indicates a higher concentration of free testosterone and a lower likelihood of hypogonadism and male infertility." (PMID 37752940, 2023). "Male infertility is affected by SHBG alterations: rs6259 and rs727428." (PMID 40427034, 2025). "Molecular docking simulations revealed the binding affinities and specific interactions between acanthoic acid and proteins related to male infertility, including SHBG, ADAM17, and DNase I, with binding affinity values of −10.2, −6.8, and −5.8 kcal/mol, respectively." (PMID 39057081, 2024). "The genetic associations of total testosterone (199,569 males), bioavailable testosterone (BAT, 184,205 males), and sex hormone‐binding globulin (SHBG, 185,221 males) and male infertility (680 cases and 72,799 controls) were extracted from previous GWASs and the FinnGen biobank." (PMID 37752940, 2023). "Among all studied phytochemicals, chlorogenic acid with a binding energy of −47.869 kcal/mol and glide docking XP score of −7.255 kcal/mol showed strong interactions with SHBG protein, which showed the potential of natural compounds as drug candidates for the treatment of male infertility." (PMID 38067423, 2023). "Therefore, we can conclude that these three compounds, with safe ADMET predictions, can be used as drugs for male infertility by inhibiting SHBG-protein activity." (PMID 36836833, 2023). "Liu and co-workers demonstrated that the presence of elevated BPA urinary levels is also associated with alterations of relevant laboratory parameters that may contribute to male infertility, namely prolactin, estradiol and sex hormone-binding globulin (SHBG)." (PMID 29051454, 2017). "However, SHBG did not exert a causal impact on male infertility or on female infertility of tubal origin." (PMID 38848344, 2024). "Therefore, natural SHBG inhibitors could be used to treat male infertility." (PMID 36836833, 2023). "Therefore, natural inhibitors of the SHBG protein could be used to treat male infertility." (PMID 36836833, 2023). "In total, 210 ligands were selected for this research and targeted against sex hormone-binding globulin (SHBG), ADAM17, and DNase I as receptor proteins to manage male infertility due to the involvement of these proteins in male infertility events." (PMID 38067423, 2023).
prediabetes (12 papers, 2013 to 2025). "Despite the low sensitivity, SHBG level below 42 nmol/L should cause closer monitoring for the fatty liver and prediabetes." (PMID 35140785, 2022). "The inverse association between SHBG and presence of prediabetes was weaker but still statistically significant in all of the adjusted models, even after further adjustment for TT and FT (model 4)." (PMID 27583401, 2016). "Among the male participants ≥65 years old, there was a strong, graded, inverse association between SHBG quartile and the presence of prediabetes after age, residence area, economic status and waist circumference were adjusted (P for trend = 0.0001, model 2)." (PMID 27583401, 2016). "In a cohort of 2,654 men, lower SHBG levels were associated with prediabetes status." (PMID 35140785, 2022). "Associations of SHBG and TT with prediabetes in age subgroup." (PMID 27583401, 2016). "Furthermore, we conducted stratified analyses to reveal the associations between serum SHBG, TT and presence of prediabetes in subgroups of age." (PMID 27583401, 2016). "The literature review revealed T2D or prediabetes associations with 10 proteins, including PON3, PLTP, and SHBG." (PMID 39589852, 2024). "Despite the low sensitivity, the SHBG level below 42 nmol/L should result in closer monitoring for the fatty liver and prediabetes." (PMID 35140785, 2022). "Our study suggests that the given SHBG levels should initiate diagnostics and treatment of fatty liver to prevent the development of prediabetes." (PMID 35140785, 2022). "Because of the influence of age on androgen, we further investigated the relationship between SHBG and prediabetes in two age subgroups." (PMID 27583401, 2016). "Compared with the NGT group, PCOS women with prediabetes had lower serum SHBG concentration." (PMID 29707577, 2018). "While, the association between TT and prediabetes did not persist after adjustment for SHBG and FT (model 4)." (PMID 27583401, 2016). "Low SHBG might be an independent predictor of incident prediabetes in Chinese male adults, especially in elderly men and this relationship might be independent from TT." (PMID 27583401, 2016). "However, in the subgroup of subjects <65 years old, neither SHBG nor TT had been detected in significant association with the presence of prediabetes in fully adjusted model." (PMID 27583401, 2016). "SHBG and AMH levels were lower in the prediabetes group than the control group (p = 0.003 and p = 0.016, respectively)." (PMID 41384021, 2025). "Furthermore, prediabetes-specific proteome features were demonstrated in proteins such as VCAM1 and severity-dependent common proteome with T2D, SHBG, or C3." (PMID 39589852, 2024). "Analyzing the data of 1139 US nationally representative group of men 20+ years old showed men with prediabetes to have lower serum total testosterone and SHBG than men without prediabetes." (PMID 30057912, 2018).